IL13 (interleukin 13)
Diseases named in the same sentence as IL13 in open-access papers (continued):
Sharing a sentence is not in itself a finding about the gene and the disease.
eosinophilia (continued). "Interestingly, we measured substantial increases in IL-4, IL-5, IL-13, and IL-17 from restimulated CD4+ T cells as well as substantial increases in eosinophilia and neutrophilia in the BAL, indicating that our one sensitization model polarizes CD4+ T cells down both Th2 and Th17 pathways." (PMID 20659336, 2010). "Importantly for the development of asthmatic symptoms, the activation of inflammatory Th2 cells through TSLP and their production of the inflammatory cytokines IL-4, IL-5, IL-13 and TNF-α triggers IgE production, eosinophilia, mucus production and fibroblast proliferation." (PMID 18724870, 2008). "Interestingly, when systemically administered to mice, IL-25 induces IL-4, IL-5 and IL-13 production from undefined non-T/non-B cells and then induces Th2-type immune responses such as blood eosinophilia and increased serum immunoglobulin E levels." (PMID 18315837, 2008). "Therefore, we may suggest that IL-13 levels may be affected by peripheral eosinophilia rather than the presence of atopy." (PMID 36326393, 2022). "Also, serum IL-13 levels may reflect peripheral eosinophilia in patients without long-term systemic steroid use." (PMID 36326393, 2022). "To test whether the detected IL-13 induced ubiquitination and proteasomal aggregation also occurs in human airway epithelia, we investigated sinunasal biopsies from patients suffering from chronic inflammation with and without eosinophilia using PLA." (PMID 31262043, 2019). "IL-4, IL-5, IL-13, ALOX15, CST1, POSTN, and CCL26 were significantly elevated in patients who had eosinophilia higher than 5%, but not IFN-γ." (PMID 40978168, 2025). "The results revealed that unlike IFN-γ, IL-4, IL-5, IL-13, ALOX15, CST1, POSTN, and CCL26 were significantly elevated in patients with eosinophilia greater than 5%." (PMID 40978168, 2025). "Eosinophilic airway inflammation induced by expressing-IL13 gene was not improved by treating with an EGFR inhibitor alone, but the combination therapy of EGFR inhibitor and dexamethasone suppressed airway eosinophilia and neutrophilic inflammation." (PMID 33217964, 2020). "IL-13 depletion prevents the development of AHR following short term challenges, but not in a seperate chronic asthma model, while suppressing eosinophilia and some features of remodelling." (PMID 18253511, 2008). "This aspect could explain the absence of blood eosinophilia in COPD and EoE during dupilumab treatment, as the IL‐33/ST2 axis may bypass the effects of IL‐4/IL‐13 inhibition." (PMID 40492692, 2025).
allergic asthma (298 papers, 2005 to 2026). A asthma with a basis in a pathological type I hypersensitivity reaction. "Although TNF-α levels remained unchanged, Th2 cytokines associated with allergic asthma (i.e. IL-4, IL-5, and IL-13) were substantially reduced in BALF following ITIH4 administration (p < 0.05)." (PMID 40410722, 2025). "Both subsets are highly proinflammatory and express various inflammatory cytokines and mediators such as Il4, Il5, Il13, Tnfsf11, Areg, Tgfb1, Calca and Furin, all of which are implicated in promoting allergic asthma and other allergic diseases." (PMID 40089475, 2025). "This process promotes T-cell proliferation, cytokine secretion (such as IL-4, IL-5, and IL-13), mucus production, and airway remodeling—all hallmark features of allergic asthma." (PMID 40724678, 2025). "Pathogenic T helper type 2 cells (pTh2) are involved in allergic asthma and secrete high levels of IL-5 and IL-13." (PMID 40089475, 2025). "Th2 cytokines—including IL-4, IL-5, and IL-13—are strongly linked to mucus production and airway inflammation, playing vital roles in the development and progression of allergic asthma." (PMID 39806495, 2025). "Meanwhile, IL-13 mainly is associated with allergic asthma induction and has less involvement in chronic processes of the respiratory system." (PMID 36648870, 2022). "IL-13, a type 2 cytokine associated with allergic asthma, has been shown to increase MUC5AC secretion and down-regulate ACE2 expression, and the effects of IL-13 on SARS-CoV-2 infection are only beginning to be explored." (PMID 35353667, 2022). "The levels of Th2-associated cytokines (IL-4, IL-5, and IL-13) increased in various allergic asthma models; MSC treatments generally restored the Th1/Th2 balance and reduced the cytokine levels, as we also observed." (PMID 35835804, 2022). "The majority of patients with allergic asthma suffer from a type 2 immune response, which is associated with Th2-mediated cytokines, including IL-4, IL-5, IL-9 and IL-13." (PMID 35744915, 2022). "Interleukin-13 (IL-13), a Th2 cytokine up-regulated in allergic asthma and associated with less severe COVID-19, protects against SARS-CoV-2 viral and cell shedding." (PMID 35353667, 2022). "The most important cytokines associated with allergic asthma are IL-4, IL-13 and IL-5, that are related to the activity of immune cells such as T cells, B cells producing specific IgE antibodies, eosinophils and mast cells." (PMID 34946286, 2021). "The hallmark Th2 immune response of allergic asthma characterized by increased secretion of IL-13 and IL-4 is directly associated with AHR, a fundamental aspect of disease symptoms and morbidity." (PMID 34924814, 2021). "IL-13 is a cytokine associated with allergic asthma (type 2) and it was observed that IL-13 decreases ACE2 expression in the nasal and airway epithelial cells." (PMID 34442770, 2021). "Elevated IgE levels in the serum is a hallmark feature of allergic asthma, where T2-cytokines IL-4 and IL-13 promote B cell differentiation, isotype class switching and IgE secretion." (PMID 34777398, 2021). "Comparison of DEGs from UNS and SEN mice confirmed that AMs express genes associated with the M2 phenotype in allergic asthma 24, likely because the allergic lung environment is enriched in IL-4 and IL-13, which drive M2 polarisation." (PMID 34764248, 2021). "It is also associated with interleukin- 4 and interleukin- 13, but these cytokines are crucially important in allergic asthma cases." (PMID 31885750, 2019). "Eosinophils have been associated with Th2 cytokines in allergic asthma; Th2 cytokines (IL-5 and IL-13) have been shown to induce eosinophilic inflammation of the airway." (PMID 30823378, 2019). "T helper type 2-associated cytokines IL-4, IL-5 and IL-13 are involved in the pathogenesis of the eosinophilic airway diseases such as allergic asthma, allergic rhinitis and NP." (PMID 30519393, 2018).
allergic asthma (continued). "Group 2 innate lymphoid cells (ILC2) are implicated in allergic asthma as an early innate source of the type 2 cytokines IL-5 and IL-13." (PMID 29250067, 2017). "In murine models of allergic asthma, using ovalbumin as a classical protein allergen, IL-13 has been implicated as an inducer of AHR." (PMID 28704401, 2017). "Allergic asthma is a T helper 2 cell (Th2)-mediated disease, in which Th2 cytokines interleukin (IL)-4, IL-5, and IL-13 are closely associated with the symptoms." (PMID 26965110, 2016). "Previous studies have shown that IL13-1055C4T, a promoter polymorphism affects expression levels and is associated with allergic asthma and chronic obstructive pulmonary disease." (PMID 24312262, 2013). "The subgroup analysis based on atopic status found that IL-13+2044A/G polymorphism was marginally associated with allergic asthma risk." (PMID 23437086, 2013). "Several studies revealed that −1055C/T polymorphism was associated with allergic asthma, altered regulation of IL-13 production and increased binding of nuclear protein." (PMID 23108822, 2012). "Additionally, IL-13 has been shown to cause mucus hypersecretion, contributing the pathophysiology of allergic asthma, as measured by MUC5AC gene expression." (PMID 38706568, 2024). "IL-13 is a primary driver in the type 2 inflammation associated with allergic asthma." (PMID 38706568, 2024). "Allergic asthma is more frequently associated with atopic dermatitis or eczema, conjunctivitis and possibly rhinitis, and it is associated with increased T2 inflammation and higher levels of cytokines such as interleukin (IL)-4, IL-5 and IL-13." (PMID 40980110, 2023). "In allergic asthma, IL-13 is a critical cytokine in the induction of the pathogenic Th2 response." (PMID 37919667, 2023). "Additionally, IL-10 and IL-1β gene polymorphisms are associated with allergic asthma in children and the association between IL-13 polymorphisms and susceptibility to childhood asthma has been extensively studied." (PMID 36313877, 2022). "The results showed that the expression levels of TSLP, IL-33, IL-4, IL-5, and IL-13 were higher in clusterB or gene clusterB than those in clusterA or gene clusterA, which suggested that clusterB or gene clusterB is highly linked to allergic asthma characterized by the Th2 immune response." (PMID 33763115, 2021). "Although there are different disease phenotypes, the hallmark of allergic asthma is a type 2 immune response, characterized by IL-4, IL-5, and IL-13 secretion by T helper 2 (Th2) lymphocytes, IgE secretion, recruitment and activation of eosinophils, mast cells, dendritic cells and epithelial cells." (PMID 34834178, 2021). "In allergic asthma, Cloots and coworkers showed that mice genetically deficient for Arg1 displayed a reduction in Il4, Il5, Il13, Ccl2, and Ccl11, all Th2-related genes, suggesting that Arg1 may regulate type 2 inflammation." (PMID 34834178, 2021). "Allergic asthma is caused by immediate hypersensitivity reaction (type I), which is initiated by antigen exposure, activating specific Th2 cells that produce IL-4, IL-5 and IL-13." (PMID 32024540, 2020). "Taken together, these results suggested that IL-13 polymorphisms may play a role in the etiology of allergic asthma." (PMID 23437086, 2013). "Functional characterization of IL-13 C-1055T polymorphism showed that T allele had opposite transcriptional effects, paralleled by distinct patterns of DNA-protein interactions at the IL-13 promoter, which has been shown to be associated with allergic asthma and abnormal IL-13 production." (PMID 21857939, 2011). "We have investigated the role of the cytokine interleukin-13 (IL-13) in the generation and persistence of airway cellular inflammation, bronchial remodeling and deterioration in airway function in a model of allergic asthma caused by chronic exposure to the aeroallergen House Dust Mite (HDM)." (PMID 20957211, 2010).
allergic asthma (continued). "IL-13 is a critical mediator of allergic asthma and associated airway hyperresponsiveness." (PMID 19116009, 2008). "Many biologics have been developed to combat type 2 inflammation and allergic asthma, with IL-4Rα being one of the main targets, since both IL-13 and IL-4 utilize it as a receptor." (PMID 40170850, 2025). "In the BAL of patients with non-allergic asthma, we measured decreased concentrations of IL-4, IL-8, IL-13, IFN-γ, C4a, C5a, and MCP-1 and increased concentrations of IL-6, IL-12p70, TNF-α, and C3a." (PMID 40725075, 2025). "The immune response to allergic asthma is primarily regulated by Th2 lymphocytes, which release IL-4, IL-5, and IL-13." (PMID 39858200, 2025). "This influx of ILC2 cells combined with the production of IL‐4, IL‐5 and IL‐13 from these Th2‐like Tregs worsens allergic asthma and food allergy." (PMID 40497455, 2025). "Allergic asthma is typically characterized by high expression of IL-4, IL-5, and IL-13, along with elevated IgE levels and eosinophil infiltration; it is a prototypical type 2 inflammation-driven disease." (PMID 40430465, 2025). "Specifically, SCFAs enhance regulatory T cell development, suppress allergic inflammation, and reduce Th2-type cytokine production, including IL-4, IL-5, and IL-13, in allergic asthma." (PMID 40529126, 2025). "Cytokine IL-13 was present in higher concentrations in the lungs of HP patients than in other ILDs or OLDs and reached significance in comparison to non-allergic asthma (p = 0.0007) and patients with amiodarone lung (p = 0.02)." (PMID 40725075, 2025). "ILC2s in the lung can control eosinophil accumulation, activation, and survival through IL-13 secretion, which is key in allergic asthma." (PMID 39861052, 2025). "Allergic asthma, which is common in childhood, exhibits a T2-high response with activation of IL-4, IL-5, IL-9, or IL-13, accompanied by eosinophilic inflammation." (PMID 40867700, 2025). "The type 2 cytokine interleukin 13 (IL-13) is a critical mediator of allergic asthma and drives goblet cell metaplasia." (PMID 38711951, 2024). "HDM is known to trigger the release of allergic asthma related cytokines, namely IL-4, IL-5 and IL-13 from Th2 cells, innate immune cells and innate lymphoid cells thereby driving eosinophil-predominant airway inflammation." (PMID 39129025, 2024). "α-Asarone inhibited the phosphorylation level of STAT3, thus inhibiting mast cell activation, inflammatory cell infiltration, and the release of IL-5 and IL-13 in lung tissue, and finally effectively alleviating allergic asthma." (PMID 39444792, 2024). "First, Th2 cells produce IL-4, IL-5, and IL-13, which promote allergic asthma, and higher Se intake skews differentiation toward Th1/Treg and away from Th2 phenotypes." (PMID 38826577, 2024). "Another major feature of the airway inflammation induced in allergic asthma is a type 2 immune response that involves the release of various cytokines, including IL-4, IL-5, and IL-13." (PMID 38790633, 2024). "In the current study, AFIFs were found to down-regulate the IL-13 level in vivo, indicating that AFIFs can inhibit the Th2 response in the allergic asthma mouse model, thus decreasing the IgE level in the serum." (PMID 39769348, 2024). "CCR4 is expressed by type‐2 inflammatory cells, including Th2 cells and innate lymphoid cells, which generate IL‐4, IL‐5, and IL‐13, and contribute to the etiology of allergic asthma." (PMID 39508721, 2024). "Another controlled study found that aqueous extract of aniseed significantly reduced the gene expression of IL-5 and IL-13 and the protein levels of inflammatory cytokines in the lung tissue of laboratory mice with allergic asthma treated." (PMID 38292939, 2024). "It has been shown that Th2 cytokines of IL-13, Il-4, and IL-5 are deeply involved in the early phase of allergic asthma pathogenesis." (PMID 39062810, 2024).
allergic asthma (continued). "Eosinophil infiltration and IL-4, IL-5, and IL-13 expression levels were also similar in HDM-induced allergic asthma LysMCreCul5fl/fl mice and Cul5fl/fl mice." (PMID 38177117, 2024). "Safranal, the main constituent of C. sativus, attenuates AHR and airway structural changes during allergic asthma and decreases IL-13 and IL-5 and other inflammatory cytokines in mouse lungs." (PMID 39263346, 2024). "CycloZ bridges this gap by dual mechanisms: it mitigates TLR4-driven immune triggers of allergic asthma and reduces downstream Th2-mediated inflammation, notably decreasing cytokines like IL-4 and IL-13." (PMID 39682780, 2024). "Particularly in allergic asthma, Th2 lymphocytes produce Th2-derived cytokines (interleukins, IL) IL-4, IL-5, IL-9, and IL-13 that promote the development of inflammatory cells, including mast cells." (PMID 38732251, 2024). "Allergic asthma has been generally considered a Th2 cell-mediated chronic immune response, while Th2 cells produce effector cytokines such as IL-4 and IL-13 to mediate respiratory symptoms." (PMID 37957139, 2023). "In experiments in vitro, the percentage of ILC2s in peripheral blood from patients with allergic asthma was significantly greater and responsive to IL-33 and IL-25, leading to the production of higher levels of IL-5 and IL-13 than healthy controls." (PMID 36674744, 2023). "Since allergic asthma is dominantly accompanied by high production of type 2 cytokines, the expression levels of interleukin- (IL-) 5 and IL-13 in lung tissues were examined by qPCR." (PMID 36846195, 2023). "Results from our study support the possible role of Nr1d1/2 (reduced mRNA expression) in chronic HDM-induced allergic asthma with heightened il4, il5, and il13 expression at ZT12." (PMID 37664635, 2023). "In a mouse model of experimental allergic asthma, local application of recombinant IL-37 lowered the secretion of IL-4, IL-5, and IL-13, thereby reducing Th2-mediated allergic airway inflammation." (PMID 38067193, 2023). "In this research, our emphasis was on Th2 cell differentiation, giventhe importance of this subset in allergic asthma due to the secretionof IL-4, IL-5, and IL-13." (PMID 38144091, 2023). "The IL-13 is an indicator of Th2 responses that alleviates allergic asthma symptoms, such as IgE synthesis, excessive mucus secretion, airway hyper-responsiveness, and fibrosis." (PMID 38983617, 2023). "Allergic asthma is a respiratory disease initiated by type-2 immune responses characterized by secretion of alarmins, interleukin-4 (IL-4), IL-5, and IL-13, eosinophilic inflammation, and airway hyperresponsiveness (AHR)." (PMID 36865540, 2023). "Imuno TF influenced cellular signaling associated to allergic asthma once downregulated STAT6 expression as well as decreased IL-4, IL-5, and IL-13 in lung and serum." (PMID 36685604, 2022). "Th2 cells contribute to the pathogenesis of allergic asthma by producing Th2 cytokines, such as IL-4, IL-5, and IL-13, leading to eosinophil accumulation in the airway wall, mucus overproduction, and IgE synthesis." (PMID 36077141, 2022). "MX1, RSAD2, IFIT1, IFI27, OAS3, and SAMD9L were markedly elevated in HDM-treated mice and positively associated with IL-5, IL-13 and MUC5AC (key mediators of allergic asthma)." (PMID 36211429, 2022). "Th2 cells secreting IL–4, IL–5, and IL–13 play a key role in the inflammatory process in allergic asthma, smooth muscle spasms, and mucus production." (PMID 36558973, 2022). "While on the other hand, Th2 cytokines such as IL-4/IL-13 can also promote the proliferation and expansion of pulmonary ILC2s in allergic asthma." (PMID 35281601, 2022). "Maternal serum in the MAA dams showed elevated levels of the T-helper type 2 allergic asthma-associated cytokines, including IL-4 (p = 0.019), IL-5 (p = 0.0004), and IL-13 (p = 0.003), confirming an allergic asthma response." (PMID 36009104, 2022).